ZNHIT3 (zinc finger HIT-type containing 3)
Synonyms: TRIP3; Hit1; PEHO
Tractability: PROTAC: ubiquitination databases record sites on it.
Gene: Protein-coding gene on chromosome 17 (36,486,629 to 36,499,310, forward strand). Ensembl gene ENSG00000273611.
Subcellular location: Cytoplasm; Nucleus
Subcellular location (Human Protein Atlas): Mitochondria
Gene Ontology:
Molecular function: protein binding; nuclear thyroid hormone receptor binding
Biological process: box C/D snoRNP assembly; maturation of LSU-rRNA from tricistronic rRNA transcript (SSU-rRNA, 5.8S rRNA, LSU-rRNA); regulation of DNA-templated transcription
Cellular component: cytoplasm; nucleus; pre-snoRNP complex
Genetic constraint (gnomAD): Loss-of-function variants: 24 observed, 17.02 expected, observed/expected ratio (o/e) 1.41, 90% interval 1.01 to 1.87. The upper end of that interval is the gene's LOEUF score, 1.87, which puts it in group 6 of 6, group 1 being the genes least tolerant of losing a copy. Missense variants: 193 observed, 168.38 expected, observed/expected ratio (o/e) 1.15, 90% interval 1.02 to 1.29. Synonymous variants: 72 observed, 61.11 expected, observed/expected ratio (o/e) 1.18, 90% interval 0.97 to 1.43.
Homologues: Orthologues: chimpanzee ZNHIT3 (99% identical), macaque ZNHIT3 (96% identical), rabbit ZNHIT3 (84% identical), guinea pig ZNHIT3 (83% identical), mouse Znhit3 (78% identical), dog ZNHIT3 (72% identical), pig ZNHIT3 (59% identical), zebrafish znhit3 (45% identical), tropical clawed frog znhit3 (41% identical), Drosophila melanogaster CG8204 (33% identical).
Diseases named in the same sentence as ZNHIT3 in open-access papers:
ZNHIT3 is named in the same sentence as 16 diseases in open-access papers, as found by Europe PMC text mining. Sharing a sentence is not in itself a finding about the gene and the disease. The quoted sentences say what the papers report.
PEHO syndrome (6 papers, 2017 to 2026). PEHO (Progressive encephalopathy with Edema, Hypsarrhythmia and Optic atrophy) syndrome is a rare neurodegenerative disorder belonging to the group of infantile progressive encephalopathies. "Bi-allelic ZNHIT3 missense variants have been reported in subjects with PEHO syndrome, while a missense in trans with a frameshift variant has recently been identified in two fetuses with hydrops from one family, resulting in pregnancy loss." (PMID 41383020, 2026). "In yeast, Nop58p depletion and the introduction of the PEHO syndrome-causing ZNHIT3 variants C11F and S29L (corresponding to p.Cys14Phe and p.Ser31Leu in human) result in lower levels of both rRNA modifying and processing box C/D snoRNAs." (PMID 41383020, 2026). "PEHO syndrome, caused by bi-allelic ZNHIT3 variants, and the phenotype observed in the proband with the homozygous NOP58 variant share several clinical features, including microcephaly, global developmental delay, early-onset seizures, and optic atrophy." (PMID 41383020, 2026). "The similarity of the CCDC88A-associated phenotype to progressive encephalopathy with edema, hypsarrhythmia, and optic atrophy (PEHO) syndrome caused by variants in ZNHIT3 was previously discussed." (PMID 40401444, 2025). "We analyze both reported PEHO syndrome-causing ZNHIT3 variants by introducing them into the HIT1 gene in yeast (hit1-C11F and -S29L) and assess their impact on yeast cell growth, ribosome biogenesis, and cellular translation." (PMID 35843310, 2022). "Here, we investigate the two PEHO-causing ZNHIT3 mutations in the model organism budding yeast to reveal the molecular basis by which they cause cellular defects and contribute to pathogenesis in PEHO syndrome." (PMID 35843310, 2022). "ZNHIT3-associated amino acid variations that cause PEHO syndrome are found within the Zf-HIT domain of the protein." (PMID 35843310, 2022). "The ZNHIT3 missense variant S31L is also found in a class of diseases with similar phenotypes to PEHO syndrome called PEHO-like syndrome." (PMID 35843310, 2022). "PEHO syndrome is a devastating neurodevelopmental disorder caused by mutations in the ZNHIT3 gene, which encodes an evolutionarily conserved nuclear protein." (PMID 35843310, 2022). "The majority of the studied ZNHIT3-associated PEHO syndrome cases to date are caused by homozygous expression of the ZNHIT3-S31L variant (yeast Hit1-S29L)." (PMID 35843310, 2022). "In this study, using budding yeast as a model organism, we reveal the molecular defects caused by the ZNHIT3 pathogenic missense mutations which cause PEHO syndrome." (PMID 35843310, 2022). "Sanger sequencing techniques identified a homozygous missense variant, L31 > S, in the ZNHIT3 gene (OMIM 604500) as the primary genetic cause of PEHO syndrome." (PMID 28954393, 2017). "The three known PEHO syndrome-associated ZNHIT3 missense variants p.Cys14Arg, p.Cys14Phe, and p.Ser31Leu allow embryonic development by destabilizing the ZNHIT3 protein leading to decreased ZNHIT3 steady-state levels in yeast and human cell culture." (PMID 41383020, 2026). "Furthermore, mutations in the ZNHIT3 gene, which encodes the human homolog of Hit1, cause a severe neurodevelopmental disorder termed PEHO syndrome (progressive encephalopathy with edema, hypsarrhythmia, and optic atrophy)." (PMID 35843310, 2022). "The precise mechanisms by which ZNHIT3 mutations lead to PEHO syndrome are currently unclear." (PMID 35843310, 2022). "Thus, loss-of-function of ZNHIT3 is suggested to cause the molecular defects observed in ZNHIT3-associated PEHO syndrome." (PMID 35843310, 2022). "Pathogenic variants in ZNHIT3 (MIM: 604500) and NOP56 (MIM: 614154) cause the progressive encephalopathy with edema, hypsarrhythmia, and optic atrophy (PEHO) syndrome (MIM: 260565) and spinocerebellar ataxia 36 (SCA36 [MIM: 614153]), respectively." (PMID 41383020, 2026).
PEHO syndrome (continued). "Mechanistically, how amino acid variations in the ZNHIT3 protein contribute to pathogenesis in PEHO syndrome remains largely unknown to date." (PMID 35843310, 2022). "ZNHIT3 was very recently shown to be defective in PEHO syndrome." (PMID 28954393, 2017). "Thus, several cases with phenotype of PEHO syndrome (Progressive encephalopathy with edema, hypsarrhythmia, and optic atrophy) and with mutated KIF1A were reported (where ‘classic’ PEHO is severe AR disorder produced by ZNHIT3 mutations)." (PMID 32746806, 2020). "Given the evolutionarily conserved function of Hit1 and ZNHIT3 and the conservation of the ribosome biogenesis and translation pathways between yeast and human, these data strongly suggest that translation can be both globally and/or specifically affected in PEHO syndrome." (PMID 35843310, 2022).
Encephalopathy (3 papers, 2022 to 2025). Encephalopathy is a term that means brain disease, damage, or malfunction. "Interestingly, for the ZNHIT3 gene encoding the zinc finger HIT domain-containing protein 3, which is known to be defective in a severe encephalopathy, and a neighboring SNP, rs4796224, the posterior probability of crossover interaction was close to one." (PMID 40203278, 2025). "Homozygous null mutations in zinc finger HIT-type 3 (ZNHIT3) and phosphatidylinositol glycan anchor biosynthesis class W (PIGW) cause encephalopathy or intellectual disability, respectively." (PMID 36373506, 2022).
Alzheimer disease (1 paper, 2024). A progressive, neurodegenerative disease characterized by loss of function and death of nerve cells in several areas of the brain leading to loss of cognitive function such as memory and language. "Our study reveals common molecular pathways in Alzheimer's disease (AD) and atherosclerosis (AS), notably in genes like BEX2, NKRF, SOD1, UBL5, ZBTB17, and ZNHIT3." (PMID 38738952, 2024).
schizophrenia (1 paper, 2021). A major psychotic disorder characterized by abnormalities in the perception or expression of reality. "Combining the cross-tissue summary metric results, we identified 3 genes passing the FDR threshold for both schizophrenia and ALS, namely ZNHIT3, GLB1L3 and TMEM194A." (PMID 35004692, 2021). "As a result, we found that ZNHIT3 (p = 1.20E-13) and TMEM194A (p = 5.12E-07) were differentially expressed between ALS patients and healthy controls in whole blood, and ZNHIT3 (p = 0.02) was differentially expressed in hiPSC-derived neurons between schizophrenia patients and controls." (PMID 35004692, 2021).
ZNHIT3 also shares sentences with these, for which no sentence is quoted: optic atrophy (5 papers); Hypsarrhythmia (4); Progressive encephalopathy (2); atherosclerosis (1); breast carcinoma (1); cancer (1); infection (1); Intellectual disability (1); neurodevelopmental disorder (1); oedema (1); Sepsis (1); tumor (1).